GBA3 (glucosylceramidase beta 3 (gene/pseudogene))
Description:
Neutral cytosolic beta-glycosidase with a broad substrate specificity that could play a role in the catabolism of glycosylceramides. Has a significant glucosylceramidase activity in vitro. However, that activity is relatively low and its significance in vivo is not clear. Hydrolyzes galactosylceramides/GalCers, glucosylsphingosines/GlcSphs and galactosylsphingosines/GalSphs. However, the in vivo relevance of these activities is unclear. It can also hydrolyze a broad variety of dietary glycosides including phytoestrogens, flavonols, flavones, flavanones and cyanogens in vitro and could therefore play a role in the metabolism of xenobiotics. Possesses transxylosylase activity in vitro using xylosylated ceramides/XylCers (such as beta-D-xylosyl-(1<->1')-N-acylsphing-4-enine) as xylosyl donors and cholesterol as acceptor. Could also play a role in the catabolism of cytosolic sialyl free N-glycans.
Synonyms: KLrP; CBG; CBGL1; GLUC
Target class: Enzyme; Hydrolase
Gene: Protein-coding gene on chromosome 4 (22,692,914 to 22,819,575, forward strand). Ensembl gene ENSG00000249948.
Subcellular location: Cytoplasm, cytosol
Genetic constraint (gnomAD): Missense variants: 532 observed, 550.28 expected, observed/expected ratio (o/e) 0.97, 90% interval 0.9 to 1.04. Synonymous variants: 212 observed, 196.12 expected, observed/expected ratio (o/e) 1.08, 90% interval 0.97 to 1.21.
Homologues: Orthologues: chimpanzee GBA3 (99% identical), macaque GBA3 (97% identical), pig GBA3 (88% identical), dog GBA3 (87% identical), rat Gba3 (86% identical), rabbit GBA3 (84% identical), guinea pig GBA3 (72% identical), tropical clawed frog gba3 (62% identical), zebrafish gba3 (46% identical), Drosophila melanogaster CG9701 (39% identical), Caenorhabditis elegans klo-1 (33% identical), Caenorhabditis elegans klo-2 (33% identical). Paralogues in human: LCT (46% identical), LCTL (45% identical), KL (41% identical), KLB (38% identical).
Diseases named in the same sentence as GBA3 in open-access papers:
GBA3 is named in the same sentence as 12 diseases in open-access papers, as found by Europe PMC text mining. Sharing a sentence is not in itself a finding about the gene and the disease. The quoted sentences say what the papers report.
Gaucher disease (3 papers, 2018 to 2024). Gaucher disease (GD) is a lysosomal storage disorder encompassing three main forms (types 1, 2 and 3), a fetal form and a variant with cardiac involvement (Gaucher disease - ophthalmoplegia - cardiovascular calcification or Gaucher-like disease). "GBA3 plays a role in the glucosylceramide metabolism and deficiency of GBA3 is, in humans, causal for Gaucher disease." (PMID 38969989, 2024). "To examine whether CDF-2::GFP was being mislocalized to lysosomes, we analyzed the distribution of CDF-2::GFP relative to an mCherry tagged form of GBA-3, a glucosylceramidase localized to degradative lysosomes that when disrupted in humans causes Gaucher disease." (PMID 30419011, 2018). "These properties may be useful to facilitate the research on the role of GBA2 and GBA3 in Gaucher disease and other disorders." (PMID 39305182, 2024).
alcoholic fatty liver disease (1 paper, 2025). Lipid infiltration of the hepatic parenchymal cells that is due to alcohol abuse. "Studies suggest GBA3 supports fatty acid oxidation and alleviates non-alcoholic fatty liver disease." (PMID 40558153, 2025).
atopic dermatitis (1 paper, 2024). "Therefore, GBA3 has been linked to atopic dermatitis and Netherton syndrome (scaling skin, hair abnormalities and increased susceptibility to atopic dermatitis)." (PMID 38969989, 2024).
Hepatic steatosis (1 paper, 2024). Steatosis is a term used to denote lipid accumulation within hepatocytes. "Histological analysis showed that GBA3 alleviated hepatic steatosis induced by a high-fat diet." (PMID 38428407, 2024).
non-alcoholic fatty liver disease (1 paper, 2025). "It is suggested that GBA3 supports fatty acid oxidation and alleviates non-alcoholic fatty liver disease." (PMID 40558153, 2025).
stomach cancer (1 paper, 2015). "We show that the amount of sialyl free N-glycans (FNGs) is dramatically reduced upon the co-expression of cytosolic sialidase NEU2 with cytosolic β-glycosidase GBA3 in human stomach cancer-derived MKN45 cells." (PMID 26193330, 2015). "The findings show that the amount of glycans is dramatically reduced upon the co-expression of cytosolic sialidase NEU2 with cytosolic β-glycosidase GBA3 in human stomach cancer-derived MKN45 cells." (PMID 26193330, 2015).
tumor (4 papers, 2019 to 2025). "Notably, all the genes associated with the tumor stage except GBA3 and PCK1 were independent predictors for OS in at least one of the two data sets." (PMID 31847435, 2019). "Both the GCS and the GBA1 expression levels were significantly up-regulated in CCA tumor tissues, whereas the GBA2 and GBA3 were down-regulated compared with matched paired non-tumor CCA tissues." (PMID 35330102, 2022). "Several statistically significantly disturbed genes (IL6, GBA3, TMEM27) show contradictory expression change trend to expression changes described in the literature and associated with tumor progression and metastasis." (PMID 31150395, 2019). "Although no specific disease or metabolic association have been identified for cytosolic β-glucosidase, with ongoing studies, it has been shown that reduced or genetic silencing of GBA3 levels in some cancer types contributes to tumor proliferation by increasing tumor chemotherapeutic resistance." (PMID 40558153, 2025). "GCS expression was higher in CCA tumor tissues than that of GBA1, GBA2, and GBA3." (PMID 35330102, 2022). "Additionally, the expression level of GCS was higher in the CCA tumor tissues than the other glucocerebrosidase (GBA1, GBA2, and GBA3)." (PMID 35330102, 2022).
cancer (3 papers, 2015 to 2022). A tumor composed of atypical neoplastic, often pleomorphic cells that invade other tissues. "The 13 overexpressed genes were reported to play a role in RCC: PAX2, NAT8, GBA3, SLC22A2 other cancer types: AOC1, HAO2, TMEM27, cell death (NPR3) or kidney metabolism: TMEM171, CYS1." (PMID 31150395, 2019). "Increased expression of glucosylceramide synthase (GCS) contributes to drug resistance and the progression of various cancers; the expression profiles of GCS (UGCG) and the genes for glucocerebrosidases 1, 2, and 3 (GBA1, GBA2, and GBA3) were therefore studied in CCA." (PMID 35330102, 2022).
metabolic disorders (1 paper, 2025). "The association between GBA3 and various metabolic disorders has been extensively investigated in recent years, yielding significant findings." (PMID 40558153, 2025). "In recent years, important results have revealed that GBA3 is associated with different metabolic diseases." (PMID 40558153, 2025).
GBA3 also shares sentences with these, for which no sentence is quoted: leukemia (1 paper); liver (1); Netherton syndrome (1).